ZNF566 (zinc finger protein 566)
Description:
May be involved in transcriptional regulation.
Synonyms: FLJ14779; MGC12515
Tractability: PROTAC: UniProt records ubiquitination sites on it; ubiquitination databases record sites on it.
Gene: Protein-coding gene on chromosome 19 (36,445,119 to 36,489,902, reverse strand). Ensembl gene ENSG00000186017.
Subcellular location: Nucleus
Subcellular location (Human Protein Atlas): Nucleoplasm
Pathways (Reactome):
Gene expression (Transcription): Generic Transcription Pathway
Gene Ontology:
Molecular function: protein binding; DNA-binding transcription factor activity, RNA polymerase II-specific; RNA polymerase II transcription regulatory region sequence-specific DNA binding
Biological process: regulation of transcription by RNA polymerase II; regulation of DNA-templated transcription
Cellular component: nucleus
Genetic constraint (gnomAD): Loss-of-function variants: 31 observed, 42.83 expected, observed/expected ratio (o/e) 0.72, 90% interval 0.54 to 0.98. The upper end of that interval is the gene's LOEUF score, 0.98, which puts it in group 4 of 6, group 1 being the genes least tolerant of losing a copy. Missense variants: 402 observed, 517.7 expected, observed/expected ratio (o/e) 0.78, 90% interval 0.71 to 0.84. Synonymous variants: 154 observed, 168.89 expected, observed/expected ratio (o/e) 0.91, 90% interval 0.8 to 1.04.
Homologues: Orthologues: chimpanzee ZNF566 (99% identical), macaque ZNF566 (97% identical), pig ZNF566 (91% identical), rabbit ZNF566 (86% identical), guinea pig ZNF566 (80% identical), mouse Zfp566 (74% identical), rat Zfp566 (68% identical), Drosophila melanogaster CG3281 (28% identical), Drosophila melanogaster Phs (26% identical), Drosophila melanogaster CG2712 (25% identical). Paralogues in human: ZNF582 (60% identical), ZNF529 (49% identical), ZNF404 (48% identical), ZNF619 (44% identical), ZNF805 (44% identical), ZNF614 (44% identical), ZNF599 (44% identical), ZFP69B (43% identical), ZNF25 (43% identical), ZFP69 (42% identical), ZNF264 (42% identical), ZFP37 (42% identical), and 50 more.
Diseases named in the same sentence as ZNF566 in open-access papers:
ZNF566 is named in the same sentence as 4 diseases in open-access papers, as found by Europe PMC text mining. Sharing a sentence is not in itself a finding about the gene and the disease. The quoted sentences say what the papers report.
Stroke (4 papers, 2019 to 2023). Sudden impairment of blood flow to a part of the brain due to occlusion or rupture of an artery to the brain. "Thus, there is an association between AF and stroke, and expression of ZNF566, PDZK1IP1, ZFHX3, and PITX2 genes favor AF-related stroke." (PMID 30760287, 2019). "A single-nucleotide polymorphism in the PITX2 and ZFHX3 genes and two other significantly associated genes, ZNF566 and PDZK1IP1, increase the risk of stroke." (PMID 35741740, 2022). "AF and stroke are related and ZNF566, PDZK1IP1, ZFHX3, and PITX2 genes are significantly associated with novel biomarkers involved in AF-related stroke." (PMID 30760287, 2019). "Finally, co-expressed DEGs of ZNF566, PDZK1IP1, ZFHX3, and PITX2 coupled with corresponding predicted miRNAs, especially miR-27a-3p, miR-27b-3p, and miR-494-3p may be significantly associated with AF-related stroke." (PMID 30760287, 2019). "Additionally, co-DEGs of ZNF566, PDZK1IP1, ZFHX3, and PITX2 link AF and stroke." (PMID 30760287, 2019).
epilepsy (1 paper, 2023). A brain disorder characterized by episodes of abnormally increased neuronal discharge resulting in transient episodes of sensory or motor neurological dysfunction, or psychic dysfunction. "FAM228B has been linked to mental health issues, ZNF566 to cardiovascular diseases, and SPIRE2 to cardiovascular diseases and epilepsy." (PMID 38681774, 2023). "The expression of ZNF566 and SPIRE2 might be related to cardiovascular diseases and epilepsy, respectively." (PMID 38681774, 2023).
tumor (2 papers, 2020 to 2022). "LINC00324 may exert tumor-promoting functions in MM through targeting the miR-512-3p/ZNF566 axis." (PMID 33193574, 2020). "In most validated samples ZNF566, TMEM150C, ENDOU were all significantly decrease in tumor tissues than in normal tissues." (PMID 36531250, 2022). "We validated the mRNA expression levels of the 4 ferroptosis-related genes (ZNF566, TMEM150C, ENDOU, MALSU1) in the tumor tissue and adjacent tissue of 10 HNSCC patients by RT-qPCR." (PMID 36531250, 2022).
ZNF566 also shares sentences with these, for which no sentence is quoted: cardiovascular diseases (1 paper).